MIR325 (microRNA 325)
Synonyms: hsa-mir-325; MIRN325
Gene: MicroRNA gene on chromosome X (77,005,404 to 77,005,501, reverse strand). Ensembl gene ENSG00000207995.
Homologues: Orthologues: chimpanzee MIR325 (100% identical).